MLANA (melan-A)
Diseases named in the same sentence as MLANA in open-access papers (continued):
Sharing a sentence is not in itself a finding about the gene and the disease.
melanoma (continued). "Tumor cells in melanoma show positivity for S-100, HMB-45, vimentin, Melan-A, tyrosinase, and microphthalmia-associated transcription factor (MITF)." (PMID 39280438, 2024). "Immunohistochemical markers and melanoma driver mutations, such as the proteins Melan-A, HMB-45, and S100, as well as the BRAF gene, respectively, provide further diagnostic information for patients with suspected malignant melanoma." (PMID 39228985, 2024). "All patients had histopathological diagnoses of oral malignant melanomas, and two of them had amelanotic melanoma confirmed by immunohistochemistry stains (Melan-A and/or PNL2)." (PMID 38668417, 2024). "Melanoma antigens A1 (MAGE-A1), gp100, or melanoma antigen recognized by T cells (MART-1/Melan-A) were found by screening cDNA expression libraries made from melanoma cell lines using tumor-reactive T-cell clones obtained from cancer patients as probes." (PMID 39127974, 2024). "Malignant melanoma is also a histologically heterogeneous tumor and can be identified by the melanoma markers Melan-A, HMB-45, SOX-10." (PMID 39465766, 2024). "Melan A and S100 were shown to be good immunohistochemical markers for feline melanomas, but while being highly sensitive, S100 has been proven to be poorly specific for melanocytic tumors." (PMID 38612342, 2024). "Melan-A is another marker found to be positive in a small percentage of HMB-45-negative melanomas, as it was detected in our case." (PMID 39712693, 2024). "For a more accurate characterization of the cell lines, we used a combination of several melanoma indicators in addition to the two indicators, MLANA and S100β, that are routinely recommended for clinical use." (PMID 38891124, 2024). "Considered vascular malformations, immunohistochemistry: Red-KI-67 (-), Red-Melan A (-), Red-Melanoma (-), Red-S-100 (-), CD31 (-), SMA (+), NF (+), GFAP (+)." (PMID 38816740, 2024). "Analyses comparing protein expression between skin and uvea melanomas indicate tumor antigens like tyrosinase, melan-A, and SOX10." (PMID 38392052, 2024). "Several IHC antibodies can be used to help distinguish melanoma from other poorly differentiated tumors, and MLANA, PNL2, TRP-1, and TRP-2 are highly sensitive and 100% specific for the diagnosis of canine oral anaplastic melanocytic tumors." (PMID 38891124, 2024). "Immunohistochemistry is crucial for the definitive diagnosis of melanoma, with markers such as Melan-A, SOX-10, HMB-45, and S-100 used to identify the tumor type." (PMID 39712693, 2024). "Endoscopy revealed a polypoid esophageal lesion, confirmed as melanoma via biopsy with positive immunohistochemical staining for Melan-A and SOX-10." (PMID 39712693, 2024). "A 2022 Oncology Pathology Working Group consensus on the most accurate methods for the diagnosis of canine melanoma cited the IHC markers MLANA, PNL2, TRP-1, and TRP-2." (PMID 38891124, 2024). "The cultivated MBM-PDOs exhibited positivity for melanoma markers, including S100, Melan A, and HMB45, consistent with their expression in the parental tumor samples." (PMID 39204387, 2024). "The IHC markers S-100, SOX10, and Melan-A contributed to better evaluation of the melanoma invasion, especially in thin melanomas, but their impact on staging and consecutive treatment remains to be confirmed by future studies." (PMID 36980327, 2023). "For example, carcinomas are positive for cytokeratins, hematopoietic malignancies express CD45, and melanoma shows Melan-A and/or HMB45-like immunoreactivity." (PMID 37240443, 2023). "To further clarify the effect of GANT61 on tumor cells at the site of bone destruction, we performed an immunohistochemical analysis by staining with anti-Melan-A antibody, a marker for melanoma." (PMID 37240209, 2023). "Melanoma antigens found in EVs are Melan-A/MART-1, glycoprotein 100 (gp100), tyrosinase-related protein (TYRP), melanoma antigen gene family (MAGE), very late antigen 4 (VLA-4) and CSPG4." (PMID 37022605, 2023).
melanoma (continued). "Quantification of CD56/MLANA double-positive melanoma cells, MLANA+ melanoma cells, CD68+ macrophages, and CD8+ T-cells in five regions of interest (ROI) showed that on average 13% of all MLANA+ cells (3,171 cells) were CD56/MLANA double-positive (430 cells)." (PMID 37563418, 2023). "The formation of pseudomelanocytic nests—clusters of Melan-A positive cells at the dermo–epidermal junction—can confound the diagnosis of melanoma in situ in the presence of lichenoid inflammation." (PMID 37958863, 2023). "To characterize lungs from neutrophil-depleted mice, we performed immunohistochemistry analysis using a melanoma marker (Melan A)." (PMID 36766767, 2023). "Melan-A is a melanocyte differentiation antigen expressed in melanocytes, melanoma and retinal pigment epithelial cells." (PMID 37427124, 2023). "In terms of diagnosis, as antibodies to melanoma antigens, Melan-A and MATT-1 are the most widely used biomarkers for the diagnosis of melanoma, with extremely high sensitivity." (PMID 37427124, 2023). "The immunohistochemical staining of the patient we reported: S100 (+), HMB45 (+), CD117 (+), Melan A (+), Ki-67 (about 90%+), consistent with the diagnosis of melanoma." (PMID 38065883, 2023). "SOX10 exhibited higher specificity (96%) compared to Melan-A (17%) in evaluating epidermal malnocytes and consequently in avoiding overdiagnosis of melanoma in situ in sun-damaged skin." (PMID 36980327, 2023). "An oncolytic adenovirus expressing a TGF-β2 shRNA and granulocyte-macrophage colony stimulating factor (GM-CSF) can significantly enhance the anti-melanoma efficacy of melanoma antigen Melan-A (MART1) in mice." (PMID 36776837, 2023). "The single case of melanoma, representing 1.5% of MUOs, was CK-negative and positive for Melan-A and S100." (PMID 36346458, 2023). "Immunolabelling for simultaneous detection of CCK2R and Melan-A (a widely recognized melanoma marker) revealed a low percentage (2–3%) of normal epidermal melanocytes that expressed the CCK2 receptor." (PMID 38069171, 2023). "In melanoma patients treated with the Melan-A peptide vaccine, circulating VLA-1-expressing Melan-A-specific CD8+ T cell numbers are correlated with better OS." (PMID 37545498, 2023). "Most importantly, going along with an increased activation of gp100- and Melan-A-specific T lymphocytes, the co-cultured melanoma cells were more efficiently eliminated by the MDA-TCR transduced T cells." (PMID 37464364, 2023). "Melan-A is particularly useful in identifying isolated tumoral melanocytes in the dermis, which can reclassify a melanoma initially diagnosed as in situ to an invasive lesion." (PMID 37958863, 2023). "The markers utilized in the conducted study, as defined by Tirosh and colleagues, successfully differentiated between various cell types, including melanoma cell (MLANA, PMEL), T cell (CD2, CD3D, CD3E, CD4, CD8A)." (PMID 37620327, 2023). "We used immunocompromised NOD/SCID IL2Rγnull (NSG) mice and injected human melan-A antigen-expressing A375 melanoma cells subcutaneously." (PMID 36812891, 2023). "The sensitivity of anti-melanoma specific antibody 45 protein and Melan-A protein is relatively high, so in clinical practice, more than 2 types of proteins are commonly used for joint detection to improve accuracy." (PMID 38065883, 2023). "Immunostaining revealed the presence of PAX6-negative cells which were positive for vimentin and the melanocyte markers Melan-A and human melanoma black-45 in the basal layer of the limbal epithelium." (PMID 36766742, 2023). "Because of the focal Melan-A expression we initially considered primary melanoma of the breast parenchyma as a differential diagnosis, which is exceptionally rare with only 15 confirmed cases in the literature." (PMID 35501497, 2023). "HMB-45 is a 100 kD glycoprotein, and studies have shown that it has higher specificity than Melan-A in the diagnosis of melanoma patients." (PMID 37427124, 2023).
melanoma (continued). "These include Melan-A, circulating tumor DNA, cell-free DNA, and melanoma-inhibitory antigens (MIAs)." (PMID 37292567, 2023). "The most frequent markers selected by the respondents included S100, SOX10, HMB45, and Melan-A, which is consistent with previous observations of markers currently used in melanoma diagnosis." (PMID 37760601, 2023). "Immunohistochemical staining using a combined anti-human Melan A/Mart1 red stain for human melanoma cells demonstrated a small, 1 mm, deposit of metastatic melanoma in the lung of a vehicle-treated mouse." (PMID 37509357, 2023). "To characterize PAX6-negative cells, we performed double immunostaining on corneoscleral tissue sections using epithelial (keratin marker, Pan-CK), stromal (vimentin), and melanocytic (Melan-A and human melanoma black−45 (HMB−45)) markers." (PMID 36766742, 2023). "In these HLA-A2:01+ melanoma cell lines, Melan-A peptide presentation induced a small but significant increase in the fraction of activated (IFNγ+CD107+) allogeneic HLA-A02 matched or autologous CD8+ T cells." (PMID 36934113, 2023). "The IHC profile showed positive tumor cells for S100, HMB45, and Melan A. Thus, a diagnosis of intramucosal melanoma was given." (PMID 36654614, 2022). "Histologic analysis was consistent with malignant melanoma displaying strong positivity for S-100, Melan A, and HMB 45 stains." (PMID 35795509, 2022). "Previous reports show that, in several melanoma cells, expression of differentiation antigens (Tyrosinase, Melan-A or CSPG4) increased after short-term treatment with BRAFi followed by a decrease at long-term, affecting T cell recognition." (PMID 36726591, 2022). "In this case, a very weak (and in retrospect, most likely artificial) staining with Melan-A contributed to the diagnosis of melanoma." (PMID 35198980, 2022). "To do that, we performed a coculture with adequate target melanoma cells (M113; presenting the specific antigen Melan-A) and CTL03.1 cells." (PMID 35967413, 2022). "Sentinel lymph nodes should be evaluated in cases of suspected malignant melanomas using serial sectioning of the node combined with immunohistochemical labeling for Melan-A and PNL-2." (PMID 35448673, 2022). "Pathologic diagnosis of melanoma requires the identification of melanin in the cytoplasm and immunohistochemistry with specific markers such as S-100, Melan A, and HMB-45." (PMID 35795509, 2022). "It should be noted that Melan A-specific T cells have unusually high frequency in melanoma patients, and even in healthy individuals with HLA-A*02 allele." (PMID 35377314, 2022). "Melanoma TAAs include the type 1 melanoma antigen recognized by T cells (MART-1, also known as Melan-A) and the melanoma-associated antigen (MAGE)." (PMID 35495634, 2022). "Triple immuno-staining detecting melan-A (MelA) (tumor area), tryptase (MAMCs), and C3 was performed on slides obtained from melanoma lesions and healthy skin biopsies and tryptase+ C3+ MAMCs were counted." (PMID 35669782, 2022). "Clinically, VLP-based vaccines against TAA Melan-A have been tested in melanoma patients showing Melan-A/Mart-A specific CD8+ and CD4+ responses in the majority of patients with sustained immune responses lasting more than a year." (PMID 35406595, 2022). "Hematoxylin and eosin (HE) staining and immunochemistry analysis of HMB-45, S-100, and Melan-A were used to identify melanoma cells." (PMID 35707354, 2022). "Addition of CpG to the Melan-A/MART-1 antigen vaccine improved the weak antigen-specific CD8+ T cell responses that were observed in previous clinical studies of patients with melanoma receiving Melan-A peptide and IFA." (PMID 35651800, 2022). "Here, we report a case of mammary Paget disease (MPD) which was misdiagnosed as melanoma in situ due to the interpretation of the staining of melanocytic markers S-100, Melan-A, and HMB-45." (PMID 35386919, 2022).
melanoma (continued). "A clinical trial of aAPC has been conducted, using MART1/Melan-A peptide pulsed aAPC to generate CTL for treating melanoma (skin) [NCT00512889]." (PMID 35456568, 2022). "As is shown, over 75% of the isolated melanocytes and melanoma cells and 86.3% of MeWo melanoma cells were Melan-A-positive." (PMID 34944864, 2021). "Again, Melan-A specific T cells from P5 and P13 patients were the most reactive against melanoma cell lines, as well as MELOE-1-specific T cells from P5, P14 and P17." (PMID 34120214, 2021). "First, all cultured MAFs were shown to express the fibroblast marker FAP and to be void of melanoma markers such as melan A and gp100." (PMID 34944793, 2021). "Melan-A-specific T-cells from P5 and P13 patients exhibited the highest reactivity against the 3 tested melanoma cell lines, compared to the 4 other populations." (PMID 34120214, 2021). "MAFs and normal dermal fibroblasts (DFs) were isolated from surgically resected melanomas and identified as Melan-A-/gp100-/FAP+ cells." (PMID 32328671, 2021). "The melanocytes and melanoma cells characterized in this study expressed tyrosinase as well as Melan-A protein, which plays a crucial role in melanosome biogenesis and is considered a marker of melanocytes and melanomas." (PMID 34944864, 2021). "In melanoma cells, β-catenin activates proteins involved in melanogenesis and pigmentation such Melan-A, dopachrome tautomerase (DCT) and tyrosinase, all through MITF." (PMID 34356645, 2021). "The induction of MLANA was confirmed to be dependent on MITF, since depletion of MITF using siRNA prevented the irradiation-dependent increase in MLANA expression in human melanoma cell lines." (PMID 33789714, 2021). "In a cytologically suspected case of melanoma included in this study, the diagnosis was confirmed by the authors through the use of immunocytochemistry with anti-Melan A and anti PNL2 markers on FNA of the oral mass." (PMID 33802040, 2021). "In comparison, transcripts of MLANA [an established marker of melanoma with prognostic properties], were more prevalent in the cancerous region." (PMID 33704427, 2021). "Surprisingly, we also detected a mild signal of melanocyte-specific protein (MLANA), which is recognized as one of the markers specific for melanoma." (PMID 34283046, 2021). "The results revealed that irradiation increased expression of both proteins, a result also reflected in the radiation-induced increased expression of MITF and MLANA in human SK-MEL-28 melanoma cells." (PMID 33789714, 2021). "TNFα induces BRN2 signaling and, in line with often mutually exclusive expression of BRN2 and MITF, it has been identified as an inhibitor of MITF and Melan A in 40 different melanoma cell lines." (PMID 34604096, 2021). "Flow cytometry analysis confirmed that the isolated melanocyte cell lines (NHM33, NHM37 and NHM51) and MM9 melanoma cell fraction expressed Melan-A, an antigen expressed by melanocytes and melanoma cells." (PMID 34944864, 2021). "All cell fractions, as well as MeWo, G-361 and WM266-4 melanoma cell lines, expressed mRNA for the MLANA, gene as revealed by qRT-PCR analysis." (PMID 34944864, 2021). "In the present case, the surgical specimen's pathological findings were positive for HMB-45, S-100, and Melan-A immunocytochemically, so the examination results qualified for malignant melanoma." (PMID 33907144, 2021). "We confirmed that the cultured melanocytes or melanoma cells displayed the tyrosinase or Melan-A protein and mRNA expression." (PMID 34944864, 2021). "For each individual patient, the frequency of MELOE-1 specific T cells was always lower than that of Melan-A-specific T cells, as previously observed in healthy donors and melanoma patients." (PMID 34120214, 2021). "PNL2 is a reliable marker in the identification of canine melanomas, with close to 100% sensitivity when used together with Melan A and tyrosinase." (PMID 34822634, 2021).
melanoma (continued). "Here we present evidence that COX-2 is overexpressed in both oral and cutaneous melanomas and that this is related to the degree of pigmentation, MI, Ki-67 proliferation index and the expression of validated melanoma markers including S-100 and melan-A." (PMID 34513965, 2021). "We screened 15 various melanoma cell lines to determine the expression of Melan-A/MART-1, gp100, and tyrosinase differentiation antigens." (PMID 34613483, 2021). "In contrast, in the second study using a coculture model of melanoma cells expressing Melan-A/MART-1 tumor antigen with Melan-A/MART-126-35-specific cytotoxic T lymphocytes (CTLs), deregulation of VCP/p97 was associated with the immune escape mechanism." (PMID 34576340, 2021). "More specific melanoma markers such as Melan-A, HMB-45, SRY-related HMG-box 10 (SOX-10), microphthalmia-associated transcription factor (MiTF) and tyrosinase, should be used together with S100 protein for accurate differential diagnosis." (PMID 34514560, 2021). "Histopathological examination and immunostaining with S-100 and Melan-A stains confirmed the diagnosis of malignant melanoma." (PMID 33633887, 2021). "This study aimed to investigate the diagnostic and prognostic utility of the conventional pan-melanoma cocktail members (HMB-45, melan-A and tyrosinase), in conjunction with SOX10 and SOX11 immunohistochemical (IHC) expression." (PMID 33801642, 2021). "When those cells were in addition loaded with the Melan-A melanoma antigen, they were able to induce repeated expansion of Melan-A-specific cytotoxic T cells with a memory phenotype 10." (PMID 33391542, 2021). "After enrichment, CTCs were stained for either pan-keratins for breast cancer and NSCLC or PMEL17/Melan-A for melanoma samples, DAPI for nuclear identification and for the leucocyte exclusion marker CD45." (PMID 34209696, 2021). "On IHC, tumour cells were positive for S-100 and vimentin, while negative for cytokeratin, epithelial membrane antigen (EMA), desmin, CD34, Melan-A, and human melanoma black (HMB-45)." (PMID 33520482, 2020). "CD8+ cytotoxic T lymphocytes (CTLs) specific to the melanoma antigen Melan-A were 111In-labeled, infused in patients, and evaluated using serial whole body and static gamma camera imaging." (PMID 32582173, 2020). "The melanoma-associated cluster includes lineage specific genes, such as MITF and MLANA, as well as markers associated with resistance to target therapy in melanoma, such as AXL and NFKB." (PMID 33202944, 2020). "Incisional biopsy with immunohistochemistry examination revealed a malignant melanoma as it strongly expressed melan A and S-100." (PMID 33738038, 2020). "Secondly, MLANA as a marker for the proliferation of melanocytes can be used to reflect brain-specific signatures of melanoma metastasis." (PMID 32266223, 2020). "CD68 and Melan A were used to highlight the macrophages and melanoma cells, respectively, if necessary." (PMID 32143442, 2020). "In line with this local progression of melanoma, Melan-A staining confirmed the expansion of the SK-MEL-28 melanoma cells in the Mel-RhS cultures, eventually leading to the partial disappearance of the epidermis at week 6 of air-exposed culture." (PMID 32507967, 2020). "Melan A staining highlights melanoma cells and was relatively homogeneous compared with VE1 staining in this case." (PMID 32143442, 2020). "Acute in vitro viability assays were used to compare the cytotoxic effect of imatinib on a melanoma cell line of spontaneous origin (B16F0) with a normal melanocyte cell line (Melan-A) in the presence of IL-12." (PMID 32450888, 2020). "ST8.24 was found to recognise the HLA A2-restricted, Melan-A-derived peptide EAAGIGILTV, a common tumour associated antigen expressed by the majority of melanoma tumours." (PMID 30930889, 2019). "Hsp70 levels were also tested in melan-A-positive cell fractions in order to specify and differentiate melanoma cells from other cellular components of the tumor." (PMID 31426515, 2019).